IL6 (interleukin 6)
Diseases named in the same sentence as IL6 in open-access papers (continued):
Sharing a sentence is not in itself a finding about the gene and the disease.
ulcerative colitis (continued). "During the development of ulcerative colitis, symptoms resulting from an aggravation of the inflammatory process appear, which will result in an exaggerated production of ROS and many cytokines (proinflammatory) such as TNF-alpha, IL-6, and IL-1 beta." (PMID 32565862, 2020). "The key role of cytokines such as TNF-α, IL-6, IL-1 β and leukotriens in the pathogenesis of IBD, particularly ulcerative colitis suggests that coriander may act through decreasing the synthesis or function of cytokines." (PMID 27222834, 2016). "Patients with ulcerative colitis only had higher levels of erythrocyte sedimentation rate (p = 0.000), CRP (p = 0.000), triglyceride (p = 0.000), Ag PLT ADP (p = 0.000), leukocyte (p = 0.001), fecal calprotectin (p = 0.000), IL-6 (p = 0.000), and TNF-α values (p = 0.000) than healthy controls." (PMID 36984554, 2023). "A recent study demonstrated that feeding mice a diet lacking vitamin K made ulcerative colitis symptoms worse, and according to the results, vitamin K could suppress the immune system by limiting the synthesis of interleukin-6 (IL-6)." (PMID 36769323, 2023). "Since IL-1β, IL-6 and TL1A are all capable of inducing IL-22 production, it is possible that pathway redundancy and IL-23-independent induction of IL-22 might contribute to ustekinumab resistance in ulcerative colitis." (PMID 36192482, 2022). "Moreover, we found that FLCWK significantly inhibited IL-6 and STAT3 mRNA expression in a rat model of ulcerative colitis, which may provide a theoretical pharmacodynamic basis for the enhancement of 5-FU efficacy in CRC by suppressing the IL-6/STAT3 pathway." (PMID 33082817, 2020). "As IL-6 was found to have increased expression in active Crohn's disease, but not in ulcerative colitis, it is not surprising that plasma PTX3 levels were increased in patients with only ulcerative colitis (because IL-1, but not IL-6, causes induction of PTX3 expression)." (PMID 22347626, 2012). "Third, only a limited set of immune markers (CD4, CD8, and IL-6) was analyzed; inclusion of additional cytokines and functional markers (e.g.,TNF-α, TGF-β, FOXP3, IL-17, granzyme B) could provide a more comprehensive understanding of immune regulation in ulcerative colitis." (PMID 41465205, 2025). "Serum IL-6, IL-8, and TNF-α levels were significantly higher in SIBO positive ulcerative colitis patients as compared to SIBO negative patients." (PMID 35630404, 2022).
acute kidney injury (238 papers, 2004 to 2026). Sudden and sustained deterioration of the kidney function characterized by decreased glomerular filtration rate, increased serum creatinine or oliguria. "The inflammatory factors associated with acute kidney injury, such as IL-6, IL-6R, IL-17, and IL-33, also showed significantly decreased expression levels by DB03476 administration." (PMID 41516327, 2025). "Clinical and experimental studies have emphasized the pivotal role of IL-6 in renal injury within kidney inflammatory diseases, including acute kidney injury (AKI), among the multitude of implicated inflammatory mediators." (PMID 38327930, 2024). "Even in humans, a higher IL-6 level has been associated with a higher rate of complete renal recovery in survivors with acute kidney injuries admitted to intensive care units." (PMID 36837598, 2023). "In PUUV-induced HFRS, severe renal failure and thrombocytopenia are associated with high plasma IL-6 levels." (PMID 34335602, 2021). "The inhibition of CD154-induced IL-6 production by chloroquine suggests the potential usefulness of this drug as a therapeutic adjunct in conditions associated with acute kidney injury." (PMID 32089648, 2020). "NF-κB promotes inflammatory cytokines (e.g., IL-6, IL-1β) production to exacerbate renal inflammation associated with acute kidney injury (AKI) and diabetic nephropathy, which is largely suppressed by JSH-23 (NF-κB inhibitor)." (PMID 32512831, 2020). "XIST silencing reduces the levels of TNF-α and IL-6 in a rat acute kidney injury model caused by I/R." (PMID 33299380, 2020). "CRRT with the oXiris filter seemed to allow effective removal of endotoxin and TNF-α, IL-6, IL-8 and IFNγ in patients with septic shock-associated acute renal failure." (PMID 31369593, 2019). "In this study, we verified that medium from Hyp-pretreated mASC significantly ameliorated levels of serum creatinine, neutrophil gelatinase-associated lipocalin, and inflammatory cytokines IL-1β and IL-6 in the serum of mice during acute kidney injury." (PMID 29890767, 2018). "In renal failure patients, elevated circulating IL-6 was identified as a risk factor for AF and increased circulating IL-6 levels have been demonstrated in coronary heart disease CHD patients with AF." (PMID 30071583, 2018). "Mice deficient in IL-6 signaling are resistant to chemically induced renal injury and IL-6 blockade has been shown to ameliorate renal function in models of acute kidney injury." (PMID 28832655, 2017). "In bivariate analysis, IL-6 and IL-8 levels at 2 and 12 hours were independently associated with the development of acute kidney injury." (PMID 19570208, 2009). "Inflammatory markers such as CRP, IL-6 and IL-18 have been linked to organ failure and could be indicators of acute kidney injury." (PMID 39563441, 2024). "In particular, the increased expression of IL-6 associated with pathological conditions is suppressed by Si-based agents in many diseases associated with inflammation, such as renal failure, renal IR injury, IR injury during flap transplantation, UC, mother-to-child infections, and neuropathic pain." (PMID 37237927, 2023). "High plasma IL-6 levels were associated with severe renal failure and thrombocytopenia in PUUV-induced HFRS and could be used as a marker of disease severity." (PMID 34335602, 2021). "The pNGAL and IL-6 were also associated with severe renal failure and severe liver failure." (PMID 34272435, 2021). "Elevated IL-6 activity was linked with a higher risk of renal failure." (PMID 34209289, 2021). "IL-6 is also associated with mortality in acute renal failure (ARF) and may be useful for predicting the clinical outcomes in patients with AKI, but supporting evidence adapted to the current KDIGO criteria are lacking." (PMID 30823904, 2019).
acute kidney injury (continued). "An increase in the concentration of IL-1β and IL-6 following renal ischaemia-reperfusion injury and bilateral nephrectomy had been noted, whilst IL-6 was shown to play a vital role in causing lung injury after acute renal failure." (PMID 30832647, 2019). "Additionally, proinflammatory cytokines such as TNF-α, IL-6, and IL-1β have been shown to be associated with cisplatin-induced acute renal failure." (PMID 24171038, 2013). "Endothelial cell damage, circulating immune complexes, complement activation, T-cell activation, and cytokine response with high levels of tumor necrosis factor-α and interleukin-6 might cause acute renal failure and peripheral consumption of platelets." (PMID 15496243, 2004). "Study results indicate that high levels of IL-6, which causes vasodilation, hypoperfusion, hypotension, and acute kidney injury (AKI), are closely associated with severe CRS." (PMID 37185744, 2023). "Other possible roles of IL-6 are the increase in fibroblast growth factor 23 (FGF23) transcription in acute kidney injury (AKI) and CKD, which is associated with increased morbidity and mortality." (PMID 33670423, 2021). "Serum levels of IL-6 have been shown to indicate a higher risk of death in patients with acute kidney injury (AKI)." (PMID 22530109, 2012). "Patient 5 had manifestations of multiple serous cavity effusion, routine blood tests indicated pancytopenia, and acute renal failure and increased IL-6 levels in plasma were observed, leading to a diagnosis of TAFRO syndrome." (PMID 39825308, 2025). "Many recent studies have reported that betanin supplementation reduces the levels of inflammatory cytokines such as TNF-α, IL-1β and IL-6 in various conditions, from stomach ulcers to testicular toxicity, from acute kidney injury to alcoholic liver disease." (PMID 41515203, 2025). "In summary, this study not only unveils a novel mechanism of IL-6/GATA2/SERPINE1-mediated cell senescence in acute kidney injury but also provides preliminary evidence for TCZ as an effective treatment for AKI-induced cell senescence." (PMID 40007559, 2025). "Histological analysis showed kidney lesions, disrupted serum biomarkers (blood urea nitrogen and creatinine) related to acute kidney injury, and elevated pro-inflammatory mediators (IL-1β, IL-6, TNF-α)." (PMID 39217203, 2025). "Baseline IL-6 may exert a protective effect on podocytes, as IL-6-deficient mice develop acute kidney injury (AKI) with podocyte dysfunction." (PMID 39749325, 2024). "In rhabdomyolysis-induced acute kidney injury model, rutin and its gold nanoparticles (Ru-AuNPs) were administrated to the mice; in consequence, expression of IL-6 mRNA in groups which received rutin or Ru-AuNPs was lower than in other groups." (PMID 38082190, 2024). "PCT dosage is superior to c-reactive protein and Interleukin 6 in predicting acute renal failure (7 n-RCTs, moderate certainty) and severe acute biliary pancreatitis (18 n-RCTs, low certainty)." (PMID 37450700, 2024). "The treatment with SeNPs coated with lycopene markedly halted the rise in the levels of TNF-α, IL-1β, IL-6, and gene expression of nitric oxide synthase in acute kidney injury-mediated renal inflammation." (PMID 37902021, 2023). "Ori has been shown to ameliorate acute kidney injury by inhibiting macrophages-mediated inflammation, and suppressing the expression of cytokines IL-2, IL-4, IL-6, IL-10, and TNF-α, suggesting that Ori had a potent anti-inflammatory response activity." (PMID 37375489, 2023). "In acute kidney injury in mice, IL6 can also be upregulated and released from the epithelial cells of the renal tubules in response to the injury and plays an essential role for renal pathophysiology." (PMID 36977223, 2023). "In acute kidney injury, IL-6 (interleukin-6), TNF-α (tumor necrosis factor-α), and IL-1 (interleukin-1) have a cardio-depressant direct impact." (PMID 37374112, 2023).
acute kidney injury (continued). "From a clinical standpoint, researchers have suggested a potential role of IL-6 in mediating renal failure through the tumor cell burden and suppressing osteoblastic activity." (PMID 38002012, 2023). "In particular, high levels of IL-6 are indicative of lung involvement, acute kidney injury, brain damage, cardiovascular events, and, finally, intestinal permeability, which allows viruses to become widespread in the general circulation." (PMID 36836679, 2023). "Further, IL-6 levels in urine can also be used as an early indicator for Acute Kidney Injury (AKI) due to the damage of the proximal tubule characteristic of the disease." (PMID 36298107, 2022). "In rhabdomyolysis associated acute kidney injury, ferroptosis-related inflammation is induced by the expression of pro-inflammatory cytokines and chemokines such as CCL-2, IL-6, and TNF-α via the TLR4/NF-κB pathway." (PMID 35153792, 2022). "Chisan® also reduced the blood level of pro-inflammatory markers IL-6, C-reactive protein, and creatinine, suggesting prevention of renal failure progression in long COVID." (PMID 36015163, 2022). "The induction of IL-6 has been observed during the development of acute kidney injury (AKI) in humans and experimental animals alike, and IL-6 is produced in different amounts by endothelial cells in response to proinflammatory signals such as TNF-α." (PMID 36364876, 2022). "si-PVT1 diminished levels of TNF-α, IL-6 and IL-1β in lipopolysaccharide-induced HK-2 cells, thus alleviating inflammation and acute kidney injury." (PMID 34775377, 2021). "Although it has been previously reported that IL-6 stimulates STAT3 phosphorylation in acute kidney injury, the mechanism of IL-6 in the STAT3/NF-kB signaling pathway remains to be investigated." (PMID 33995063, 2021). "In the acute kidney injury study, inflammatory cytokines such as IL-1β, IL6, and TNF-α were measured in mice 16 h after intraperitoneal injection of LPS." (PMID 34327209, 2021). "TLR4 is even involved in regulating the processes of the infiltration of leukocytes in the kidney during ischemic acute kidney injury and the release of IL-6." (PMID 34638569, 2021). "The evaluation of different inflammatory mediators such as TNF-α, IL-1β, IL-6 and NF-κB verified the protective effects of linalool (50 and 100 mg/kg) against cisplatin-induced acute kidney injury." (PMID 33126443, 2020). "The canonical pathways including acute phase response-, EIF2-, TREM1-, IL-6-, HMBG1-, PPAR signaling, and LXR/RXR activation were associated with acute heart, pulmonary, and renal failure." (PMID 32154187, 2020). "Inflammatory cytokines such as IL-6, IL-1β and NF-kB also reported contributes in the development of renal failure and level of them was found to ameliorated in Cinnamtannin A2 treated 5/6 nephractomized rats." (PMID 32385622, 2020). "To assess direct tissue injury, we measured kidney mRNA expression of KIM‐1 and NGAL, which are elevated in renal failure, and the inflammatory markers IL‐6, IL‐1β, and TNFα." (PMID 31102342, 2019). "On presentation, the patient was found to have acute kidney injury, thrombocytopenia, elevated inflammatory markers, elevated interleukin-6 (IL-6), and endocrinopathy." (PMID 31453020, 2019). "Other studies have reported the induction of IL-6 expression during the development of acute kidney injury both in humans and in experimental animal models; however, a study of IL-4 expression was not performed." (PMID 31583036, 2019). "Renal levels of IL-1β, IL-18, and IL-6 and neutrophils have been reported to be higher in cisplatin-induced acute kidney injury." (PMID 30691208, 2019). "ATF3 was demonstrated interacted directly with histone deacetylase 1 (HDAC1) and recruited HDAC1 into the ATF/NF-κB sites in the IL-6 and IL-12b gene promoters to protect against acute kidney injury." (PMID 28912732, 2017).
acute kidney injury (continued). "NF-κB is a well-known regulator of the transcription of inflammatory gene including TNF-α, IL-1β, and IL-6 during acute kidney injury." (PMID 28465474, 2017). "Investigations demonstrated that IL-6 signaling has a critical role in the harmful inflammatory process in acute kidney injury and its expression has been observed both in human and experimental animal models." (PMID 28670523, 2017). "Serum IL-6 is increased in patients with acute kidney injury and ALI, and it has been thought to be a biomarker of a poor outcome of lung injuries." (PMID 26690120, 2015). "Increases in kidney IL-6 protein levels have been reported following cisplatin treatment in an acute renal failure model." (PMID 25189223, 2014). "In some occasion of catabolic status, the chronic inflammation associated with renal failure often can lead to elevated levels of TNF-α and IL-6." (PMID 22761655, 2012). "Studies have shown that targeted disruption of IL-6 attenuates acute kidney injury induced by ischemia-reperfusion or mercury." (PMID 23272241, 2012). "For IL-6, Kielar et.al 2005 found that in mouse model of ischemic renal injury, macrophages infiltrate the area of the vascular bundles of the outer medulla, these macrophages produce IL-6, and this IL-6 exacerbates ischemic murine acute renal failure." (PMID 22196041, 2011). "• The proinflammatory cytokine IL-6 increases early (at six hours) in patients with acute kidney injury due to cardiopulmonary bypass." (PMID 20942931, 2010). "In acute renal failure, it has been demonstrated that plasma IL-6 levels are elevated and that high levels predict mortality." (PMID 20500875, 2010). "Serum resistin concentrations were closely correlated to inflammatory parameters such as C-reactive protein, leukocytes, procalcitonin, and cytokines such as IL6 and TNF-α, as well as associated with renal failure and liver synthesis capacity." (PMID 19545363, 2009). "When we analyzed the association between cytokine levels and the requirement for prolonged mechanical ventilation, an interaction between IL-6 levels and acute kidney injury was detected (P = 0.06)." (PMID 19570208, 2009). "Moreover, research from Guo X and the team indicated that IL-6 accelerates renal fibrosis following acute kidney injury by activating the Wnt/β-catenin pathway." (PMID 39499704, 2024). "Acute kidney injury is characterized by a high inflammatory state, reduced cytokine clearance, and elevated levels of systemic cytokines, such as interleukin (IL)-17A, IL-6, IL-8, IL-1β, IL-12, and tumor necrosis factor (TNF)-α, which aggravate lung injury and increase the risk of lung infection." (PMID 39724279, 2024). "In rat models of renal failure, IL-6 expression was increased, and fibrosis was promoted through increased collagen expression; however, it was suggested that a Si-based agent may alleviate fibrosis by suppressing its expression." (PMID 37237927, 2023). "In LPS treated renal tubular epithelial NRK-52E cells (AKI), emodin also inhibited LPS-induced TLR2, NF-κB, TNFα, IL-1β and IL-6 expression in vitro, which may contribute to the immune regulation of emodin in LPS-induced acute kidney injury." (PMID 35744949, 2022). "In addition, cytokines, such as TNF, IL-2, or IL-6, contribute to acute kidney injury and renal failure, as reported in critically ill COVID-19 patients." (PMID 36235704, 2022). "IL-6 expression is correlated with the onset and severity of acute renal failure." (PMID 36117588, 2022). "IL6 is a key proinflammatory cytokine in the progression of acute kidney injury, and its downregulation by AP39 may contribute to the improved outcomes of the SNTAP group compared to the SNT group." (PMID 33802753, 2021). "Previously, it was determined that although IL-6 deficiency did not accelerate the development of systemic injury, it did accelerate progression of cisplatin-induced acute renal failure." (PMID 33805488, 2021).